MGA (MAX dimerization protein MGA)
Description:
Functions as a dual-specificity transcription factor, regulating the expression of both MAX-network and T-box family target genes. Functions as a repressor or an activator. Binds to 5'-AATTTCACACCTAGGTGTGAAATT-3' core sequence and seems to regulate MYC-MAX target genes. Suppresses transcriptional activation by MYC and inhibits MYC-dependent cell transformation. Function activated by heterodimerization with MAX. This heterodimerization serves the dual function of both generating an E-box-binding heterodimer and simultaneously blocking interaction of a corepressor (By similarity).
Synonyms: KIAA0518; MAD5; MXD5; FLJ12634; POF26
Tractability: PROTAC: UniProt records ubiquitination sites on it; ubiquitination databases record sites on it; its protein half-life has been measured.
Gene: Protein-coding gene on chromosome 15 (41,621,134 to 41,773,081, forward strand). Ensembl gene ENSG00000174197.
Subcellular location: Nucleus
Subcellular location (Human Protein Atlas): Nucleoplasm; Cytosol
Pathways (Reactome):
Gene expression (Transcription): Transcriptional Regulation by E2F6
Gene Ontology:
Molecular function: protein binding; DNA-binding transcription factor activity, RNA polymerase II-specific; RNA polymerase II cis-regulatory region sequence-specific DNA binding; DNA-binding transcription factor activity; protein dimerization activity
Biological process: cell fate specification; heterochromatin formation; negative regulation of DNA-templated transcription; negative regulation of transcription by RNA polymerase II; regulation of transcription by RNA polymerase II; positive regulation of DNA-templated transcription; regulation of DNA-templated transcription
Cellular component: MLL1 complex; RNA polymerase II transcription repressor complex; chromatin; nucleoplasm; nucleus; PRC1 complex; protein-containing complex
Genetic constraint (gnomAD): Loss-of-function variants: 36 observed, 241.26 expected, observed/expected ratio (o/e) 0.15, 90% interval 0.11 to 0.2. The upper end of that interval is the gene's LOEUF score, 0.2, which puts it in group 1 of 6, group 1 being the genes least tolerant of losing a copy. Missense variants: 3,329 observed, 3,694.6 expected, observed/expected ratio (o/e) 0.9, 90% interval 0.88 to 0.93. Synonymous variants: 1,283 observed, 1,318.5 expected, observed/expected ratio (o/e) 0.97, 90% interval 0.93 to 1.02.
Homologues: Orthologues: chimpanzee MGA (98% identical), macaque MGA (96% identical), dog MGA (89% identical), pig MGA (89% identical), rabbit MGA (86% identical), rat Mga (83% identical), guinea pig MGA (82% identical), mouse Mga (81% identical), tropical clawed frog mga (38% identical), zebrafish mgaa (25% identical), Drosophila melanogaster ocm (7% identical), Caenorhabditis elegans mab-9 (4% identical), and 9 more. Paralogues in human: TBX2 (6% identical), TBX15 (6% identical), TBX5 (5% identical), TBX18 (5% identical), TBX3 (5% identical), TBX4 (5% identical), TBX6 (5% identical), TBX1 (5% identical), TBX22 (5% identical), TBR1 (4% identical), TBX20 (4% identical), EOMES (4% identical), and 4 more.
Diseases named in the same sentence as MGA in open-access papers:
MGA is named in the same sentence as 46 diseases in open-access papers, as found by Europe PMC text mining. Sharing a sentence is not in itself a finding about the gene and the disease. The quoted sentences say what the papers report.
lung adenocarcinoma (9 papers, 2014 to 2024). A carcinoma that arises from the lung and is characterized by the presence of malignant glandular epithelial cells. "The loss of MGA in lung adenocarcinoma cells, which occurs in ~8% of lung adenocarcinoma patients, was shown to lead to an upregulation of MYC- and E2F6-target genes, resulting in an increase in cancer cell proliferation and invasiveness." (PMID 38454121, 2024). "MGA is significantly mutated in lung adenocarcinoma and participates in the negative regulation of MYC." (PMID 35223840, 2022). "Focusing on MGA, we note that it is mutated or deleted in 53 of 507 (10%) lung adenocarcinoma patients (TCGA) and in 233 of 3696 (6%) patients sequenced through the GENIE project." (PMID 34236315, 2021). "The majority of MGA mutations in lung adenocarcinoma are truncating mutations, and enrichment in nonsense mutations at the MGA locus across all cancers is statistically significant, suggestive of a tumor suppressive role for the protein." (PMID 34236315, 2021). "Loss-of-function MGA mutations with MYC amplification in lung adenocarcinoma have been newly described and MGA gene was identified by SomInaClust analysis in our study." (PMID 32998690, 2020). "Inactivating mutations in MGA may contribute to solid tumor development and have been detected in colorectal cancer, adenocarcinomas of the lung and small‐cell lung cancers." (PMID 33811746, 2021). "Given the overlap of MGA targets we observed in our mouse models, we examined human lung adenocarcinoma TCGA data to assess whether the expression of these genes correlates with MGA loss in patients." (PMID 34236315, 2021). "We chose to further investigate MGA function in lung cancer since a substantial percentage of lung adenocarcinoma patients (6–10%) harbor MGA alterations." (PMID 34236315, 2021). "A recent study revealed that ectopic expression of MGA in lung adenocarcinoma cell lines retards their growth." (PMID 34236315, 2021). "Lastly, we note that, in both the lung adenocarcinoma cells and colon organoids, MGA deletion is also accompanied by downregulation of multiple genes." (PMID 34236315, 2021). "Here we demonstrate that MGA inactivation dramatically accelerates tumor progression in a murine model of lung adenocarcinoma and triggers oncogenic conversion in human-derived colon tissues." (PMID 34236315, 2021). "In lung adenocarcinoma cell line NCI-H2009, a PTPN12 pseudogene caused an 8 kb target-site deletion that removed the promoter and first exon of MGA." (PMID 24714652, 2014). "Heterozygous somatic alterations of MGA, the most common of which lead to loss-of-function truncation/deletion of the MYC-like bHLH domain, occur in 5% of all cancers and are commonly seen in lung adenocarcinoma, endometrial carcinoma, and colorectal cancer." (PMID 38454121, 2024). "However, most striking are the high frequency of genetic alterations sustained by the MAX dimerizing repressor, MGA (pronounced mega), across a wide range of cancers including 8% of lung adenocarcinomas." (PMID 34236315, 2021). "In lung adenocarcinoma, the molecular function of MGA appears to be antagonistic to that of MYC." (PMID 33920880, 2021). "Moreover, MGA deletion in human lung adenocarcinoma lines augmented invasive capabilities." (PMID 34236315, 2021). "In summary, we demonstrate that MGA acts as a bona fide tumor suppressor in vivo and have uncovered a critical role for MGA and the atypical PRC1.6 complex in lung adenocarcinoma." (PMID 34236315, 2021). "Our candidates also included several genes typically considered TSGs, including CDKN1A (bladder carcinoma, 9.2% in TCGA), KMT2A (kidney carcinoma, 0.6%), MGA (ovarian carcinoma, 1.5%), PTEN (high-grade glioma, 14.2%), RB1 (lung adenocarcinoma, 5.0%), SMAD4 (ovarian carcinoma, 0.5%)." (PMID 34313788, 2021).
lung adenocarcinoma (continued). "To investigate whether MGA loss leads to similar functional consequences in vitro, we used either shRNA- or CRISPR-based approaches to delete or knock down MGA in A549 and NCI-H23 lung adenocarcinoma lines." (PMID 34236315, 2021). "Analysis of TCGA data suggests that MGA loss in lung adenocarcinoma patients is not frequently accompanied by amplification or highly increased expression of MYC family proteins, although we show that MYC is required for growth and survival of both MGA wild-type and mutant cells." (PMID 34236315, 2021).
lung carcinoma (9 papers, 2021 to 2024). "Together, these data identify tumor suppressor inactivation of MGA as a highly recurrent contributor to smoking-associated lung cancer." (PMID 39052387, 2024). "MGA was found with loss-of-function mutations in lung cancers and colorectal cancers." (PMID 40453362, 2024). "Furthermore, MGA mutations were most frequently seen in lung cancer (LUAD, 69%), prostate cancer (TGCT seminoma, 46%), and HPV-negative head and neck cancer (TGCT seminoma, 46%)." (PMID 35801728, 2022). "Inactivation of MGA is frequent in human cancer, and a recent study has demonstrated that MGA functions as a tumor suppressor in murine models of lung carcinoma and in colorectal cancer organoids, partly due to the de-repression of MYC target genes." (PMID 34572909, 2021). "Our genomic occupancy analysis in both mouse and human lung cancer lines is entirely consistent with the widespread recruitment of ncPRC1.6 subunits with MGA-MAX binding sites on genomic DNA." (PMID 34236315, 2021). "(G–I) Quantification of protein levels of the indicated proteins in MGA WT (blacks bars) vs. MGA mutant (white bars) lung cancer lines." (PMID 34236315, 2021). "MGA loss was accompanied by a decrease in L3MBTL2 levels, as we had observed in our lung cancer models." (PMID 34236315, 2021). "MGA, encoding MAX dimerization protein, is a tumor suppressor gene in lung cancer." (PMID 33927616, 2021). "First, addback of a mutant form of MGA lacking this region fails to retard the growth of MGA-deficient human and mouse lung cancer lines." (PMID 34236315, 2021). "Similar enrichments of SGMs were seen in other core TSGs such as RB1, NF1, and ARID1A and emerging TSGs such as MGA, a transcription factor of the MYC network that suppresses growth and invasion in cellular and mouse models of lung cancer." (PMID 37922356, 2023). "MGA binds and stabilizes PRC1.6 complex members in lung cancer cells." (PMID 34236315, 2021). "Additionally, EGFR, MGA, SMARCA4, ATM, RBM10 and KDM5C which are lung cancer related genes are mutated only in LUAD but not in LUSC." (PMID 33672117, 2021).
colorectal cancer (7 papers, 2021 to 2024). A primary or metastatic malignant neoplasm that affects the colon or rectum. "Overall, our data in colorectal cancers further extend the concept that MGA functions as a tumor suppressor in multiple tissue types and that normal organoids can serve as an in vitro system for study of early events that are triggered by MGA loss of function." (PMID 34236315, 2021). "Recent studies provide evidence for a tumor suppressive role for the gene MGA (MAX dimerization protein) in colorectal cancer." (PMID 33920880, 2021). "MGA has also been reported to contribute to MYC-mediated pathway in colorectal cancer cell lines." (PMID 36249027, 2022). "We also provide preliminary evidence for a tumor suppressive role for MGA in colorectal cancer." (PMID 34236315, 2021). "To study MGA’s role in colorectal cancer initiation, we utilized a CRISPR-based approach to inactivate MGA in normal human colon organoids and confirmed that MGA levels were decreased in sgMGA organoids compared to those infected with the vector control." (PMID 34236315, 2021). "Given the frequent inactivation of MGA across diverse cancer types, it will also be critical to further characterize MGA- and PRC1.6-mediated transcriptional attenuation in other malignancies with MGA alterations, such as colorectal cancer and diffuse large B-cell lymphoma." (PMID 34236315, 2021).
leukemia (3 papers, 2021 to 2024). A malignant (clonal) hematologic disorder, involving hematopoietic stem cells and characterized by the presence of primitive or atypical myeloid or lymphoid cells in the bone marrow and the blood. "The reported mutations of MGA in pediatric RUNX1::RUNX1T1 leukemias are heterozygous, somatic mutations at variable variant allele frequencies and result in the deletion of the MYC-like bHLH domain, potentially resulting in a protein with altered or abolished function." (PMID 38454121, 2024). "Collectively, our data highlight MGA as an important regulator of pathways critical for leukemia development, such as MYC activation, cell cycle, and oxidative phosphorylation, and that loss of function mutations identified in patients can functionally cooperate with the RUNX1::RUNX1T1 oncoprotein." (PMID 38454121, 2024). "Lastly, MGA truncations in leukemia due to intronic polyadenylation also occur in this region." (PMID 34236315, 2021).
acute myeloid leukemia (2 papers, 2023 to 2024). Acute myeloid leukemia (AML) is a group of neoplasms arising from precursor cells committed to the myeloid cell-line differentiation. "Loss-of-function mutations in MGA have been commonly identified in several hematological neoplasms, including acute myeloid leukemia (AML) with RUNX1::RUNX1T1, however, very little is known about the impact of these MGA alterations on normal hematopoiesis or disease progression." (PMID 38454121, 2024). "MGA has also been identified as a common genetic alteration in hematological neoplasms, including acute myeloid leukemia (AML), chronic lymphocytic leukemia (CLL), natural killer/T-cell lymphoma, B-cell acute lymphoblastic leukemia (B-ALL), and T-cell acute lymphoblastic leukemia (T-ALL)." (PMID 38454121, 2024).
diffuse large B-cell lymphoma (2 papers, 2021). "Consistent with this, MGA emerged as one of the top hits in a genome-wide CRISPR screen for tumor suppressors in DLBCL (diffuse large B-cell lymphoma) lines." (PMID 34236315, 2021). "However, frequent mutations in some subunits, such as MGA and BCOR/BCORL1, as well as generally high mutation rates in cancers such as diffuse large B-cell lymphoma (DLBCL) and cholangiocarcinoma of the bile duct (CHOL) point to specific roles for Polycomb subunits in tumor suppression." (PMID 34617019, 2021).
metastatic tumors (2 papers, 2015 to 2023). "For metastatic tumors from GENIE, a total of sixteen candidate genes had significantly higher SNV frequencies in MMR-d tumors, of which six genes (KMT2D (33.3%), JAK1 (28.3%), FAT1 (21.7%), ERBB4 (20.0%), KMT2A (20.0%), and MGA (20.0%)) had a SNV frequency ≥ 20% in MMR-d tumors." (PMID 36675550, 2023).
non-small cell lung carcinoma (2 papers, 2021). A group of at least three distinct histological types of lung cancer, including non-small cell squamous cell carcinoma, adenocarcinoma, and large cell carcinoma. "We further confirmed decreased E2F6, L3MBTL2, and PCGF6 protein levels in MGA mutant human non-small cell lung cancer lines H2291 and Lou-NH-91 when compared to wild-type lines such as NCI-H1975, NCI-H23, and 91T." (PMID 34236315, 2021).
Atrophy (1 paper, 2024). Any weakening or degeneration, especially through lack of use. "Genetic variants associated with decreased levels of pathogenic proteins ITGB6 (rs8099840), TLR5 (rs1403631, rs75118229), F7 (rs6046), HERC5 (rs406936) and MGA (rs704) were associated with preserved brain volumes over time, including in regions susceptible to infection-specific atrophy." (PMID 39143319, 2024).
breast tumors (1 paper, 2007). "The frequency of MGA hypermethylation in breast tumors suggests that it may serve to accentuate the activity of Myc, even in the absence of Myc amplification or overexpression." (PMID 18091988, 2007).
head and neck cancer (1 paper, 2019). A primary or metastatic malignant neoplasm affecting the head and neck. "Relatively frequent mutations were also detected in several other IntOgen-defined cancer drivers such as MGA, PABPC3, NR4A2, NCOR1 and MACF1; of these PABPC3, NR4A2, NCOR1 and MACF1 are detected as mutational cancer drivers in head and neck cancer in IntOgen." (PMID 31427592, 2019).
lymphoma (1 paper, 2025). A malignant (clonal) proliferation of B- lymphocytes or T- lymphocytes which involves the lymph nodes, bone marrow and/or extranodal sites. "As an important tumor suppressor gene, inactivating mutations of MGA are common in lymphoma and may lead to high expression of c-Myc by releasing the inhibition of the MYC signaling pathway." (PMID 41561755, 2025).
myeloid leukemia (1 paper, 2024). A clonal proliferation of myeloid cells and their precursors in the bone marrow, peripheral blood, and spleen. "Mutations in ATM, MGA, KMT2A, MLLT10, NSD1, and TET2 have been commonly identified in several hematological neoplasms, including both acute lymphoid and myeloid leukemia." (PMID 38672648, 2024).
myeloma (1 paper, 2025). "Despite the distinct burden of subclonal mutations, some CH mutations were conservative among MM, AL, POEMS, and MGUS, including lymphoid and myeloid CH mutations, such as those in KMT2D, FAT1, MGA, and SYNE1, and myeloma driver genes like ZFHX3 and DIS3." (PMID 40152254, 2025). "Recurrent lymphoid CH mutations (in FAT1, KMT2D, MGA, and SYNE1) and myeloma driver gene mutations (in ZFHX3 and DIS3) were found in the dominant clonal and subclonal plasma cell populations." (PMID 40152254, 2025).
neuropathy (1 paper, 2016). A disorder affecting the nervous system that manifests with pain, tingling, numbness, and/or muscle weakness. "The TTR variant segregates into all branches in which offspring reported neuropathy in deceased parents, whereas the segregation of the MGA variant cannot fully explain the parental phenotypes." (PMID 27212199, 2016).
pancreatic adenocarcinoma (1 paper, 2021). "Because MYC has been reported to repress anti-tumor immune responses in tumors, including in Kras-driven lung and pancreatic adenocarcinomas, MGA may normally act to limit MYC repression of these genes." (PMID 34236315, 2021).
Primary amenorrhea (1 paper, 2024). "However, proband POI-588 in our study, harboring heterozygous LoF variants in both MGA and ERCC6, presented with primary amenorrhea, further supporting the likelihood that genetic burden may affect severity of phenotypes." (PMID 39545409, 2024).
rheumatoid arthritis (1 paper, 2022). A chronic, systemic autoimmune disorder characterized by inflammation in the synovial membranes and articular surfaces. "We use molecular interaction and colocalisation analyses to identify multiple nuclear regulatory pathways linking meQTL loci to phenotypic variation, including UBASH3B (body mass index), NFKBIE (rheumatoid arthritis), MGA (blood pressure), and COMMD7 (white cell counts)." (PMID 34980917, 2022).
ulcerative colitis (1 paper, 2016). An inflammatory bowel disease involving the mucosal surface of the large intestine and rectum. "The a-DMR within the promoter of the MGA promoter also shows this trend, with the SNP rs28374715 in this LD block associated with ulcerative colitis." (PMID 27663977, 2016).